CD80 (CD80 molecule)
Diseases named in the same sentence as CD80 in open-access papers (continued):
Sharing a sentence is not in itself a finding about the gene and the disease.
prostate carcinoma (11 papers, 2006 to 2025). A carcinoma that arises from epithelial cells of the prostate gland. "Interestingly, miR-21 could also promote tumor invasion and is associated with increased BCR in prostate cancer, which may explain our finding that CD80 expression predicts BCR-free survival in a combined analysis of CIT and TCGA cohort." (PMID 32909077, 2021). "Conversely, CD80 is an M1 macrophage marker and decreased in enzalutamide-resistant prostate cancer which is directly promoted by immunosuppressive signaling." (PMID 38698344, 2024). "Studies on prostate cancer, hematological malignancies, renal cell carcinoma, and NSCLC have associated low serum CD80 expression with progression-free survival while high levels are associated with enhanced invasiveness and poor prognosis." (PMID 37256148, 2023). "Earlier studies report the presence of DCs with impaired CD80/86 expression in several tumors, including renal cell carcinoma and prostate cancer." (PMID 33530408, 2021). "This suggests that FTO overexpression in lung and prostate cancers may impair CD70/CD80-mediated immune activation." (PMID 40565233, 2025). "Soluble T cell regulatory proteins CD28, CD80, CTLA4, and HVEM were correlated with both biochemical recurrence and progression risks in prostate cancer." (PMID 40659985, 2025). "Resveratrol induces growth arrest through activation of FOXO transcription factors in prostate cancer cells and suppresses the immune response through CD28/CTLA-4 and CD80 co-stimulatory pathways." (PMID 25501752, 2014).
squamous cell carcinoma (11 papers, 2019 to 2026). A carcinoma arising from squamous epithelial cells. "In squamous cell carcinoma, CD80 (FC = 0.88, P = .014), CTLA4 (FC = 0.80, P < .01), and IDO1 (FC = 0.84, P = .020) expression was lower in HRD cohorts compared with HRP." (PMID 41533995, 2026). "For example, after the ACT immunotherapy, stem cell‐like squamous cell carcinoma cells upregulate CTLA4 through the expression of CD80, thereby directly inhibiting cytotoxic T cell activity." (PMID 37638338, 2023). "In squamous cell carcinoma, tumour-initiating cells acquired the immune checkpoint molecules CD80 and CD276 to evade immunological surveillance from cytotoxic lymphocytes during local recurrence and metastasis." (PMID 37875589, 2023). "Another subset of TGF-β-responsive squamous cell carcinoma stem cells acquired CD80 to modulate cytotoxic T cell attack during immunotherapy." (PMID 36494785, 2022). "A subset of squamous cell carcinoma stem cells was found refractory to adoptive T cell transfer-based immunotherapy through acquiring CD80 to dampen cytotoxic T cell attack." (PMID 36494785, 2022). "For instance, scRNA-seq identified a subset of tumor-initiating stem cells in squamous cell carcinoma, which selectively express CD80 molecule and bind to the CTLA4 on cytotoxic T cells and thus damage the activity of T cells." (PMID 34722635, 2021). "Meanwhile, squamous cell carcinoma stem cells were reported to selectively express CD80 to suppress cytotoxic T cell–mediated tumoricidal activity, resulting in refractoriness to adoptive T‐cell transfer therapy." (PMID 33932112, 2021). "We observed higher expression of immune checkpoint ligands (PVR, NECTIN2, CD274, CD80, and CD86) in the tumor cells at the invasive front of the squamous cell carcinomas." (PMID 41309580, 2025). "Metastatic initiating cells can also co-opt CTLA-4 immune checkpoint to avoid T cell activation—for instance, TGF-β-induced CSC expression of CD80, leading to T cell inhibition through the CD80-CTLA-4 axis in pre-clinical models of squamous cell carcinoma." (PMID 33498251, 2021).
cervical carcinoma (10 papers, 2010 to 2024). A carcinoma arising from either the exocervical squamous epithelium or the endocervical glandular epithelium. "The expression of BTLA, KLRK1, CD80, and CD28 reduced the risk score, and these were suggested as protective factors in cervical cancer prognosis." (PMID 39312339, 2024). "Studies have examined the effect of CD86 on CIN and cervical cancer: CD80/CD86-positive dendritic cells are reported to be more abundant in the cervices of women with high-risk HPV positivity but no CIN lesions." (PMID 39302712, 2024). "In the present study, the data demonstrated that in cervical cancer, autophagy promoted the phagocytosis of macrophages, induced the expression of CD80 and CD86 and resulted in antigen presentation and immune activation, which in turn limited the tumor growth." (PMID 33390854, 2021). "In this work, we show that B lymphocytes from cervical cancer patients respond to treatment with sCD40L and IL-4 by increasing the CD80+CD86+ population, therefore potentially increasing their ability to activate T cells." (PMID 29975708, 2018). "The expression of CD80 and CD86 in the CIN group (CD80: 49.52 ± 21.74%; CD86: 46.92 ± 15.24%) was lower than that of the healthy individuals (CD80: 51.23 ± 17.16%; CD86: 49.02 ± 21.58%), and lowest in patients with cervical carcinoma (CD80: 39.59 ± 17.39%; CD86: 42.54 ± 19.51%)." (PMID 20565840, 2010). "By testing 11 cervical cancer tissue and 11 adjacent normal tissues specimens using TMA, CD80 and CD28 expression are lower in cervical squamous cell carcinoma tissues." (PMID 34852825, 2021). "Genes related to immune promotion, such as CD86 and CD80, have a significant negative regulatory relationship, indicating that MLK4 may affect the infiltration of immune cells in Cervical cancer by regulating the expression of immune checkpoints." (PMID 37594950, 2023). "Moreover, in cervical cancer, when macrophages are cultured in a medium with human sera, CD206++ is the marker of M2a macrophages, CD163++ is the marker of M2c macrophages, and CD80++ is the marker of M1 and M2b macrophages." (PMID 35805111, 2022). "Nonrecombinant BCG also increased the expression of these receptors on DCs, which is in contrast to the results reported by Manickam and Sivanandham showing reduced expression of CD80 but not CD86 on BCG- or PPD-stimulated DCs from patients with cervical cancer." (PMID 26339658, 2015).
metastatic disease (10 papers, 2005 to 2024). "We genetically engineered RCC-26 cells to express CD80 together with selected cytokines in order to enhance their natural immunogenicity and we have initiated a two-center trial comparing vaccine variants expressing CD80 with IL-2 or IL-7 in HLA-A*0201-matched patients with metastatic disease." (PMID 16045799, 2005). "Based on our data, the detected elevated populations of CD80+ and CD86+ lymphocytes in the patients with metastatic disease can also be included in the group of markers for CRC." (PMID 39456247, 2024). "miR-18a treatment led to increasing percentages of F4/80+IFNγ+, F4/80+IL-12+, F4/80+CD80+, and decreasing percentages of F4/80+ transforming growth factor beta (TGFβ)+, F4/80+CD206+ and F4/80+ IL-10+ detected in the liver metastatic tumor bearing mice." (PMID 27028860, 2016).
Stroke (10 papers, 2014 to 2024). Sudden impairment of blood flow to a part of the brain due to occlusion or rupture of an artery to the brain. "Transcriptional analysis confirmed a reduction in expression of co-stimulatory genes in the spleen known to be expressed by macrophages 1–5 days after experimental stroke including Cd40, Cd80, Cd86, Icam1, Tnfsf9, which encodes 4-1BBL, and Cd274." (PMID 29872438, 2018). "Conversely, the percentage of CD80+/CD16+ events was unaffected in patients; meanwhile, the percentage of CD80+/CD14+ events significantly increased only 24 h after stroke." (PMID 34201498, 2021). "Conversely, the percentage of CD80+/CD16+ events was unaffected after stroke, whereas the percentage of CD80+/CD14++ events was significantly increased 24 h after the insult as compared to CT." (PMID 34201498, 2021). "The influx of DCs into the brain increases dramatically post-stroke and is associated with elevated expression of co-stimulatory molecules MHCII, CD40, and CD80." (PMID 31736685, 2019). "Our results showed that post-stroke treatment of GF mice with a cocktail of IPA and IAld significantly increases expression of MG AHR, MHC-II, and CD80." (PMID 37790313, 2023). "Expression of the activation markers CD80 and CD86 after stroke remained unaffected by vehicle and t-PA treatment on cDC and macrophages from the cLN at the 24 h time point (data not shown)." (PMID 30972077, 2019). "Post-stroke treatment of GF mice with a cocktail of microbiota-derived indole-based ligands of AHR regulated MG-mediated neuroinflammation and molecules involved in antigen presentation (increased CD80, MHC-II, and CD11b)." (PMID 37790313, 2023). "CD80/CD28 interactions played a prominent regulatory role for the CD8+ T-cells and the PD-1/PD-L2 interactions were dominant in controlling the CD4+ T-cell responses in WT mice, after stroke." (PMID 25157219, 2014). "Unsupervised analysis of the flow cytometry data with respect to the seven surface parameters of CD45, CD11b, MHC-II, CD80, P2RY12, and Tmem119 detected several subsets of MG, lymphocytes and infiltrating monocytes visualized as a phonographic comparison of the vehicle and treated GF stroke brains." (PMID 37790313, 2023). "Through Spearman correlation analysis, we determined that the CD206 MFI of peripheral blood monocytes showed a significant positive correlation with TREM2 MFI in stroke patients, while the CD80 MFI showed a negative correlation with the TREM2 MFI, which was consistent with our data in animal models." (PMID 33845849, 2021). "Also, CD80/CD28 interactions played a prominent regulatory role for the CD8+ T-cells and the PD-1/PD-L2 interactions were dominant in controlling the CD4+ T-cell responses in WT mice after stroke." (PMID 25157219, 2014). "Interestingly, the CD80/CD28 interactions appeared to play a prominent regulatory role for the CD8+ T-cells while the PD-1/PD-L2 interactions were dominant in controlling the CD4+ T-cell responses in WT mice, after stroke." (PMID 25157219, 2014). "As expected, monocytes from stroke patients with high urine sodium concentration expressed less CD206 than normal monocytes from diet stroke patients, while no differential expression of CD80 was recorded." (PMID 33845849, 2021).
acute lymphoblastic leukemia (9 papers, 2015 to 2024). Leukemia with an acute onset, characterized by the presence of lymphoblasts in the bone marrow and the peripheral blood. "In contrast, one study revealed that acute lymphoblastic leukemia cells have low expression of costimulatory molecules including CD80 and suggested that this probably contributes to the absence of a host T cell-stimulated immune response." (PMID 30040869, 2018). "Interestingly, acute lymphoblastic leukemia (ALL) blasts that were nonresponsive to BiTE therapy had higher surface PD-L1 expression, and blocking of CD80 signaling in preclinical ALL models led to decreased efficacy." (PMID 36073543, 2022). "However, in contrast to stable CD80 and/or CD86 expression on primary DLBCL cells, PD-L1 cell surface expression on pediatric B-cell precursor acute lymphoblastic leukemia (ALL) depends on induction by IFN-γ and TNF-α." (PMID 38340727, 2024).
Allergy (9 papers, 2013 to 2024). An allergy is an immune response or reaction to substances that are usually not harmful. "Thus, besides investigating the allergy-associated response, levels of CD11C+CD103+ DC as well as DC expressing mutation markers, including CD80, CD86, and MHCII in MLN, were also determined using flow cytometer in the current study." (PMID 34177885, 2021). "In PBMCs isolated from patients with allergies, there was an upregulation of HLA-DR, CD80, and CD86 with amoxicillin, while in PBMCs from cirrhotic patients, norfloxacin impaired CD80/86 expression." (PMID 39596729, 2024). "Regarding M2 macrophages, M-IL4 enhanced HLADR and CD80 expression, but also CD206 and CD23, the latter being involved in allergic reactions." (PMID 29593730, 2018). "Importantly, decreasing the expression of the co-stimulatory molecules CD80 and CD86 in DCs has been reported as a potential target for the treatment of allergic diseases." (PMID 33746954, 2021). "As CD80 and CD86 have been found to mediate the necessary costimulatory signals to evoke Th2 polarization involved in allergy, CD80 and CD86 upregulation induced by rBla g 7 in DCs may contribute to the subsequent allergic responses." (PMID 24204099, 2013). "Notably, neither 24 nor 48 hours of co‐incubation of MA::Art v 1 VNP, Art v 1::GPI VNP, empty VNP (10 μg/mL each), or rArt v 1 protein (1 μg/mL) with bone marrow‐derived dendritic cells (BMDC) of TCR/DR1 allergy mice upregulated CD40, CD80, CD86, or MHC class II expression, when compared to medium." (PMID 30035810, 2019).
lung adenocarcinoma (9 papers, 2019 to 2025). A carcinoma that arises from the lung and is characterized by the presence of malignant glandular epithelial cells. "By using bioinformatics methods, elevated CD80 was found to improve the prognosis of patients with lung adenocarcinoma." (PMID 39575257, 2024). "The genes that increased with fivefold following co‐culture with all lung adenocarcinoma cell lines were CD80 (B7‐1), IL‐7, IL‐15, and TNF." (PMID 34907653, 2022). "It suggests that CD80 may be a potential prognostic and therapeutic target in lung adenocarcinoma." (PMID 39575257, 2024). "Additional research has been conducted, such as lung adenocarcinoma cells that have been transfected with hCD40L and hGM-CSF (NCT00601796) or B7.1 (CD80) and HLA A1 (NCT00534209)." (PMID 39179939, 2025). "Interestingly, our results showed that CD80 was significantly downregulated in several cancer types including LUAD (lung adenocarcinoma), LUSC (lung squamous cell carcinoma), and THCA (thyroid cancer); these results suggest that the role of CD80 might be varied by cancer types." (PMID 35814211, 2022). "We found that the expression of CD28, CD80, andCD86 was markedly reduced, suggesting that PSMB6 may decrease their expression to reduce the binding between CD80/CD86 and CD28, ultimately leading to immune evasion in lung adenocarcinoma cells." (PMID 39507618, 2024).
non-small cell lung carcinoma (9 papers, 2019 to 2024). A group of at least three distinct histological types of lung cancer, including non-small cell squamous cell carcinoma, adenocarcinoma, and large cell carcinoma. "It was shown to downregulate IFNγ-induced MHC-I expression in non-small cell lung cancer cell lines, and CD80/CD86 in dendritic cells stimulated with lipopolysaccharide, thereby reducing T-cell stimulatory capacity." (PMID 35655783, 2022). "Immune checkpoint inhibitors targeting the CTLA-4/CD80 or PD-1/PD-L1 axes constituted a major breakthrough in the treatment of several types of tumors, such as inoperable or metastatic melanoma and non-small-cell lung cancer (NSCLC)." (PMID 33923750, 2021). "Research on non-small cell lung cancer (NSCLC) has shown that exosomes produced from tumor cells overexpressing Rab27a can promote DC maturation by upregulating MHC II and the CD80 and CD86 costimulatory markers." (PMID 39062506, 2024). "CD80 and CD86 are moderately expressed in some tumors, such as non-small cell lung cancer, especially on the surface of cancer cells, thus helping cancer cells to escape from the immune attack." (PMID 31440272, 2019). "Moreover, homoharringtonine induced changes in immune cell features by decreasing the expression level of IL12 and the overexpression of CD80, CD86, CD69, CD80+, and CD86−in B220 + B cells and B cells, respectively, in non-small cell lung cancer." (PMID 34975465, 2021). "Additionally, the immune checkpoint proteins CD80 (B7-1) and CD86 (B7-2) are expressed on the surfaces of both tumor and immune cells, serving as significant prognostic biomarkers in various cancers, including bladder cancer and non-small cell lung carcinoma." (PMID 38904744, 2024).
bladder cancer (8 papers, 2016 to 2024). "Furthermore, in bladder cancer patients, risk scores were inversely linked with the expression levels of immune marker genes (CD8A, CD80, etc.)and immune activation‐related genes (IL6, IFNG, etc.)." (PMID 37771276, 2023). "Similarly to the TC-1/dCD80-1-induced tumors, anti-CTLA-4 administered as a single therapy reduced the progression of another tumor type, i.e., mouse bladder cancer induced by the MB49 cell line with low CD80 expression." (PMID 33923750, 2021).
Hodgkins lymphoma (8 papers, 1997 to 2024). A heterogeneous group of malignant lymphoid neoplasms of B-cell origin characterized histologically by the presence of Hodgkin and Reed-Sternberg (HRS) cells in the vast majority of cases. "CD80 expression was also found in Reed-Sternberg(R-S) and immune cells in 50 histopathologically confirmed cases of Hodgkin’s lymphoma." (PMID 39575257, 2024). "In this study, we analyzed the expression and potential role of CTLA-4 and CD80 signaling pathways related to immune suppression and disease progression in the tumor microenvironment of various subtypes of Hodgkin Lymphoma." (PMID 37305822, 2023). "In the nodular sclerosis subtype, the distribution of CD80 expression and intensity in both HRS cells and immune cells showed that 5 out of 9 cases had 10-50% expression, and 6 out of 9 cases had 2+ intensity in HRS cells." (PMID 37305822, 2023). "We found that CTLA-4 expression was higher in T cells than in antigen-presenting cells (APC), and CD80 expression was higher in APC than T cells in the immune cells of the Hodgkin lymphoma microenvironment." (PMID 37305822, 2023). "We compared the expression of CTLA-4 and CD80 in the immune cells of the Hodgkin lymphoma microenvironment." (PMID 37305822, 2023). "Immunomodulators aimed to achieve blocking of inhibitory molecules on the cell surface of immune effectors (i.e., Anti PD-1, anti-CD30, anti CD52, anti-CTLA-4, and anti-CD80), were approved for the treatment of patients with Hodgkin Lymphoma (HL)." (PMID 31357735, 2019). "Remarkably, the differences in activated B cells (CD19+/CD80+ and CD18+/CD86+) persisted when 14 HIV(+) AHCT recipients with Hodgkin lymphoma were compared directly to HIV(-) AHCT recipients by Wilcoxon rank sum analysis (p<0.0185)." (PMID 34539628, 2021). "Lymphoma cells express CD70, CD80, CD86, and PD-L1 immune checkpoints that downregulate effector T-cells including Th17, and that allowed clinical approval of CIs for Hodgkin’s lymphoma (HL) and primary mediastinal B-cell lymphoma." (PMID 31947775, 2020). "The interference of vaccinia virus-infected cell culture supernatant was confirmed by flow cytometry using the CD80- and CD86-positive human cell line KM-H2 (Hodgkin lymphoma) and soluble recombinant CTLA4-Fc." (PMID 30918073, 2019).
Hyperglycemia (8 papers, 2013 to 2024). An increased concentration of glucose in the blood. "Protection was extended up to 63 days, at which point 65% of immunised and DOX-treated BPTL mice developed hyperglycaemia, probably because of the robust immune attack conveyed by CD80 overexpression." (PMID 26813254, 2016). "Multifunctional P. melaninogenica in saliva is also associated with oral squamous cell carcinoma and is causative of periodontitis, Alzheimer’s disease mortality, hyperglycemia, [and MHCII, CD80 and IFN-γ upregulation in salivary gland epithelial cells in Sjögren’s syndrome." (PMID 34367522, 2021).